NRAS (NRAS proto-oncogene, GTPase)
Diseases named in the same sentence as NRAS in open-access papers (continued):
Sharing a sentence is not in itself a finding about the gene and the disease.
tumor (continued). "FoundationOne next-generation sequencing showed that her PD-L1 tumor proportion score was 0%, tumor mutation burden was low, and there were no reportable alterations in BRAF, ERBB2, KRAS, or NRAS." (PMID 40026534, 2025). "Finaly, the tumor mutational burden (TMB) was low, and no abnormalities were detected in BRAF, NRAS, HRAS, NTRK1/2/3, RET, or TERT." (PMID 40277780, 2025). "While KRAS, NRAS, and BRAF hot-spot mutations are very important drivers of tumorigenesis and tumor progression, it is important to note that they are not the only intrinsic features of colonic tissues dictating its consequences for tumorigenesis." (PMID 39857025, 2025). "In parallel, comprehensive molecular profiling of the tumor tissue was performed to identify potentially actionable genomic alterations; however, no targetable mutations (e.g., BRAF, NRAS, c-KIT) were identified, thereby limiting the use of targeted therapies." (PMID 41384184, 2025). "No BRAF, NRAS, NF1 or TERT promoter mutations were detected, though all tumor samples harbored additional mutations." (PMID 38903495, 2024). "Considering the tumor’s response to therapies, which varies based on its molecular environment, molecular profiling also plays a crucial role, and it is targeted mainly towards BRAF, NRAS, and c-KIT genes." (PMID 39519055, 2024). "Genomic testing revealed a KRAS, NRAS, BRAF wild type and a dMMR tumor." (PMID 39064004, 2024). "Herein, we reveal that unlike chronic developmental Sox9 deletion, the acute and therapeutic elimination of Sox9 reduces overall cHCC-CCA tumor burden in Akt-YAP1 but not the Akt-NRAS model." (PMID 39273023, 2024). "Let-7 targets multiple oncogenes (RAS, c-MYC, HMGA2 to date) and the prominent mechanisms by which let-7 exerts a tumor suppressive role is by repressing the translation of the three RAS proteins (HRAS, NRAS, and KRAS) and c-MYC, a downstream effector of RAS-ERK signaling." (PMID 38637419, 2024). "In contrast, when examining the NRAS gene, we observed that numerous tumor types did not achieve significant t-test p-values (green arrows), despite apparent trends." (PMID 39455841, 2024). "In a hepatocyte OIS model in vivo, ectopic expression of NRAS(G12V) does not induce tumours, in part owing to OIS-driven immune clearance." (PMID 39112713, 2024). "In addition, genes related to tumor spreading, cell migration, and cytoskeletal reorganization were also up-regulated in vitro and in vivo, such as CDC42, DNMBP, CAPG, NRAS, BCL9L, etc.." (PMID 39063079, 2024). "TAA administration was associated with inflammation and fibrosis, increased tumor density in combination with SB/AKT/NRas, but did not appreciably increase tumor size." (PMID 39254423, 2024). "Overall, a recommendation on the frequency of molecular testing of BRAF and NRAS status can be approximated to include at least two metastases, if not all metastases that arise over the course of tumour progression." (PMID 38127894, 2024). "The other high-NRAS cluster, which included tumour cells, exhibited elevated Notch1 and TGFβ signalling." (PMID 39112713, 2024). "Finally, the limited availability of tumour biomarkers (e.g. BRAF, NRAS) restricts our analysis and comprehensive understanding of the biological behaviour of the tumour in patients with mCRC." (PMID 39177674, 2024). "Here, we revealed that liver-specific developmental Sox9 elimination using Alb-Cre;Sox9(flox/flox) (LKO) and CRISPR/Cas9-based tumor-specific acute Sox9 elimination (CKO) in SB-HDTVI-based Akt-YAP1 (AY) and Akt-NRAS (AN) cHCC-CCA models showed contrasting responses." (PMID 39273023, 2024). "Indeed, we showed that targeting NRAS via either molecular knock-down or pharmacological inhibition with lonafarnib did not affect pAKT signalling neither in vitro nor in vivo, suggesting that lonafarnib could overcome this feedback activation and result in a stronger anti-tumour effect." (PMID 38653965, 2024).
tumor (continued). "We also found that G6PD, NRAS and HRAS may have a positively moderate correlation with most of IGCs in Tumor cell/APC/DC group than in T cell group." (PMID 37143953, 2023). "The deleted regions contained the tumour suppressors CDKN2C, SDHB, and SFPQ in 1p and CDKN2A in 9p in metastatic samples and the tumour suppressors BCL10 and NOTCH2 and the oncogenes JAK1 and NRAS in 1p in the non‐metastatic sample group." (PMID 37622176, 2023). "The same group demonstrated that miR-145-5p tumor suppressive function was also performed through other targets, namely NRAS and VEGFA (vascular endothelial growth factor A), thus impairing invasion and angiogenesis in vitro, and also tumor growth and angiogenesis in vivo." (PMID 36765733, 2023). "Among them, ERBB4 and NPM1 are presumably involved in cSCC tumorigenesis; in addition, GNAQ, GNAS, JAK2, NRAS, IDH2, and CTNNB1 may be related to tumor metastasis." (PMID 36780540, 2023). "Ras protein (HRAS and NRAS) are common oncogenes and mutant RAS could be considered as a driver of tumor initiation and maintenance." (PMID 37143953, 2023). "Notably, modules containing alterations in NRAS, BRAF and SRC showed similar statistics since only four, eight and twelve mutant tumours were present in CMS4." (PMID 37666855, 2023). "BRAF V600 mutations were identified in 52.8% of patients’ tumor samples (19/36), RAS mutations in 30.6% (11/36), and non-BRAF/non-NRAS mutations in 19.4% (7/36)." (PMID 36901733, 2023). "According to the Canadian Consensus Practice Guidelines on tumour biomarker testing for mCRC, the minimum biomarker testing required across all Canadian jurisdictions for mCRC patients requires testing for KRAS/NRAS, BRAF, and MMR/MSI prior to the initiation of 1L therapy." (PMID 37754511, 2023). "Mutational status in tumor tissue comprised 14 patients (67%) with KRAS mutations, nine without detection of KRAS, NRAS, or BRAF mutations (wild-type), and four without available mutational testing." (PMID 37903871, 2023). "Different from KRAS and BRAF (V600E) mutation, none of the clinical characteristics, such as age, gender, tumor sites, histological type, differentiation, TNM stage, lymphovascular invasion, and perineural invasion, was associated with NRAS mutation." (PMID 36862900, 2023). "Finally, NRAS overactivation was also defined by strong CD133 cancer stem cell antigen upregulation, already present in early tumours." (PMID 37946160, 2023). "For chromosome 18q11.2‐q12 no‐loss patients with RAS (KRAS and NRAS)/BRAF wildtype tumors and left‐sided location of the primary tumor, anti‐EGFR in the first‐line is a viable alternative, now recommended solely beyond the first‐line." (PMID 35489024, 2022). "The baseline characteristics, including sex, sidedness, tumor grade, histology, stage at diagnosis, KRAS/NRAS mutation status, and MSI status, were not different between the two groups." (PMID 35625987, 2022). "Furthermore, the clinical rationale of molecular tumor characterization regarding BRAF, KIT or NRAS, as well as the therapeutic value of immunotherapy, chemotherapy and targeted therapy, has not yet been deeply explored and clearly established in MM." (PMID 35052829, 2022).
tumor (continued). "NRAS mutation was associated with elevated CEA, the presence or absence of mucus in the tumor, the depth of tumor invasion, and clinical manifestations." (PMID 35837115, 2022). "Tumor intrinsic features, such as KRAS, NRAS and BRAF mutational status, did not interact with the survival effect of 25(OH)D levels (p = 0.773) and this was in line with a recently published review." (PMID 35681576, 2022). "Of note, in 19 cases, sequence variation not previously detected in tumor tissue that emerged under therapy (five NRAS, 14 KRAS)." (PMID 34873826, 2022). "Interestingly, NRAS alteration forms a Dual Lethal Dependency with PTPN11: it confers tumor sensitivity to NRAS inhibition and resistance to PTPN11 inhibition." (PMID 35805023, 2022). "We sought to understand general practice patterns, the influence of molecular diagnostics (e.g., testing for KRAS, NRAS, BRAF, and MSI), tumor sidedness, and patient-centric factors on treatment selection utilizing in-person surveys and three hypothetical patient case scenarios." (PMID 36005180, 2022). "Collectively, our data suggest circSMARCA5 as an upstream regulator of the expression of TS miRNAs 126-3p and 515-5p and their downstream targets IGFBP2 and NRAS mRNA in GBM cells, extending our knowledge on the disrupted tumor suppressive pathways mediated by circSMARCA5 in GBM cells." (PMID 36430152, 2022). "Lastly, LZTR1, characterized as a negative regulator of RAS39, no longer acted as a tumor suppressor under low glutamine conditions, and correspondingly oncogenic NRAS became less essential." (PMID 36115844, 2022). "NRAS activates various signaling pathways, such as the Phosphoinositide 3-Kinase (PI3K)/AKT and Nuclear Factor-kappa-B (NF-κB) pathways, to enhance the proliferation, migration, and invasion of tumor cells." (PMID 35339759, 2022). "Further, we did not collect data on molecular abnormalities in primary tumour, e.g. the presence of activating mutations in the KRAS, NRAS and BRAF, or microsatellite instability and defective DNA mismatch repair (dMMR)." (PMID 33971834, 2021). "For patient 3, all manifestations presented a similar morphology, with the NRAS-mutant tumor showing smaller cells and lacking the initial prominent nucleoli." (PMID 34072863, 2021). "In KRAS-mutated endometrial cancer cells, individual deletion of WT HRAS or NRAS limited proliferation in cancer cells, but not xenograft tumor growth." (PMID 33924994, 2021). "This is due to an absence of inhibitors directed against mutant NRAS, along with adaptive and acquired resistance of this tumor type to inhibitors in the MAPK pathway." (PMID 35187538, 2021). "Molecular study: Molecular analysis of the tumor tissue was first performed by Indiana University Molecular Pathology Laboratory and showed that the tumor was microsatellite stable with no mutation in BRAF, KRAS, and NRAS genes." (PMID 34940081, 2021). "In addition, our data on the Fusobacteria relationship with the tumor molecular characteristics of MSI and KRAS/NRAS/BRAF status were consistent with studies using frozen tissue specimens and another study with FFPE tissue specimens." (PMID 34650531, 2021). "The clinical characteristics including age, gender, tumor location, tumor size, tumor differentiation, AJCC disease stage, KRAS/NRAS/BRAF mutation status, non-quantitative FOBT, serum CEA and CA19-9 were matched between oCRC group and yCRC group." (PMID 34799562, 2021). "Next, the Cox regression hazard model was performed using the following confounder variables: age, gender, tumor stage, type of tumor (primary/metastatic), and presence/absence of BRAF, NRAS, and NF1 mutations." (PMID 34502169, 2021). "A potential limitation of our study is that MAPK1, KRAS, and NRAS SNPs were analyzed in the blood and not in tumor samples." (PMID 34828284, 2021).
tumor (continued). "Certain miRNA also functions as tumor suppressors, for instance, the let 7 family suppresses tumor development and metastasis via targeting key oncogenic genes like high-mobility group AT-hook 2 (HMGA2), members of the RAS family (NRAS, KRAS, and HRAS), and MYC." (PMID 35145899, 2021). "An additional 65 studies contained relevant data for KRAS, NRAS, or BRAF mutation status and tumor sidedness but did not report data specific to the mCRC population or data for mutation status by tumor sidedness." (PMID 31856410, 2020). "Only one patient without baseline mutations in ctDNA nor tumor tissue gained mutations in KRAS, NRAS, and BRAF at progression in ctDNA." (PMID 31350822, 2019). "For patients with mCRC, KRAS, NRAS and BRAF tumour genotyping has therefore a major impact on clinical management and genotyping results should be available within 7 working days to ensure a rational first-line treatment selection based on validated molecular data." (PMID 31265477, 2019). "Indeed, KRAS and NRAS mutant tumours and to a lesser extent BRAF mutant tumours are highly sensitive to combinations of PARP with MEK/ERK inhibitors in vitro, whereas for KRAS mutant models this evidence is available in vivo." (PMID 31374917, 2019). "The non-redundancy of KRAS and NRAS functions, and the high level of tumor heterogeneity observed in CRC, however, suggest wide-ranging clinical and therapeutic implications." (PMID 31816869, 2019). "In patients with treatment benefit (n = 21), no mutations in KRAS, NRAS, and BRAF were detected in tumor tissue." (PMID 31350822, 2019). "Although we detected NRAS Q12D mutant ctDNA at 1.4 copies per mL of plasma at one time point in patient 6, we did not detect TERT C228T mutant ctDNA at any time point in this patient, although it was detected in the tumor." (PMID 30719207, 2019). "Additional factors considered in the adjustment model, comprising tumor colorectal subsite location, smoking history, BMI, and mutations of KRAS, NRAS, BRAF, and PIK3CA, did not meet the 10% change in coefficient criteria for confounder selection." (PMID 31367996, 2019). "The AJCC‐UICC have included other prognostic factors such as degree of differentiation, R classification, circumferential resection margin, tumor regression score, CEA level, lymphovascular invasion, perineural invasion, microsatellite instability, KRAS, NRAS, and BRAF." (PMID 31069966, 2019). "In an exploratory analysis, data on KRAS status in ctDNA were combined with previously obtained data on KRAS/NRAS status in tumour tissue and patient outcome assessed by presence/absence of these mutations." (PMID 29362371, 2018). "As for the mutational status of the KRAS, NRAS and BRAF genes, no discordance was observed between the primary tumours and the metastases." (PMID 30029640, 2018). "Meanwhile, KRAS, NRAS and BRAF are potential tumor-driven genes themselves." (PMID 30416987, 2018). "Using BMT, we show that CXCR1‐mediated tumor cell–endothelial interactions are not sufficient for NRAS‐driven lung metastasis, which also requires the concurrent involvement of myeloid cells that express CXCR2." (PMID 28341702, 2017). "In our study, we observed that none of the two POLE‐positive tumors presented NRAS or BRAF mutations, but tumor T286 exhibited the p.Glu542Lys PIK3CA mutation and tumor T368 displayed the p.Lys117Asn KRAS mutation." (PMID 29072370, 2017). "We show that overexpression of NRAS and AKT induced invasive tumor growth." (PMID 28114956, 2017). "However, only approximately 40 % of CRC patients with tumours wild-type for KRAS, NRAS and BRAF benefit from such therapy, and patients who initially respond eventually become resistant to these drugs." (PMID 27160084, 2016). "By contrast, mutant NRAS does not affect the initial homeostasis or tumor progression but inhibits the ability of intestinal epithelial cells to undergo programmed cell death in response to chronic exposure to apoptotic stimuli." (PMID 27636997, 2016).
tumor (continued). "When compared in FFPE tumor samples with or without mutations, miR-31-5p/3p expression levels were found not to be associated with KRAS/NRAS mutational status (P = 0.901 and P = 0.813, respectively)." (PMID 26497852, 2015). "PCR-based DNA sequencing analysis of the patient’s tumor specimen revealed no EGFR, BRAF, KRAS, NRAS, PI3KCa, or c-kit mutations." (PMID 25126591, 2014). "Patients with BRAF-mutation positive tumours and BRAF wildtype tumours had comparable irDCRs (38% vs 39%), as did patients with or without NRAS mutations (57% vs 49%)." (PMID 24885479, 2014). "In tumours that have BRAF mutation [HR (95%CI)=0.81 (0.46, 1.43), p=0.47] and in NRAS mutants, low PTEN level did not significantly influence prognosis [HR 95%CI)=0.88 (0.29, 2.69), p=0.82]." (PMID 24830350, 2014). "This suggested that targeting the PIK3CA effector arm alone was not sufficient to prevent tumor growth in the NRAS mutant line." (PMID 19492075, 2009). "The genomic background of CRC, including alterations in KRAS, NRAS, PIK3CA, AKT1, BRAF, and the tumor’s MSI status, may modulate both the abundance and biological relevance of the immune regulators TIGIT and CD155, thereby affecting immune evasion and clinical outcome." (PMID 41596586, 2026). "However, it cannot be excluded that the coexistence of NRAS and RET alterations in this case is due to the presence of heterogeneous tumor populations derived from two distinct tumor foci colliding in the same lesion, a possibility well described in the literature." (PMID 41123735, 2025). "In our patient, the tumor was negative for the common BRAF, KRAS, and NRAS mutations." (PMID 41169288, 2025). "In “negative hyperselected” patients, the absence of resistance-associated mutations (e.g., KRAS, NRAS, BRAF V600E, and EGFR extracellular domain mutations) ensures that the EGFR pathway remains a primary driver of tumor progression, making these tumors more susceptible to EGFR blockade." (PMID 40076838, 2025). "The Hippo, PI3K/AKT, and tumor microenvironment signaling pathways, responsible for cell proliferation, migration, and invasion, were more enriched in differentially expressed predicted target genes (LATS2, NRAS, PPP2CB, etc.)in cells transfected with mimics of ISO-miR-1246_a and/or ISO-miR-1246_G." (PMID 38474054, 2024). "Molecular VAF assays were developed for the quantitative detection of RAS variants at single-nucleotide resolution positive for NRAS, HRAS, and KRAS in tumor tissues but not in the adjacent healthy tissue, which were verified by Sanger sequencing (eFigure 1 in Supplement 1)." (PMID 38758552, 2024). "Variations within genes of the MAPK signaling pathway in TECs, such as amplifications in CDC42, HSPB1, NRAS, and deletions in AKT1, MAPK1, might reveal their significance in HCC, possibly related to their roles in tumor growth and progression, particularly in signaling pathways." (PMID 39484208, 2024). "Interestingly, SOX9-DNMT1 is partially involved only in Akt-NRAS tumor formation but not in Akt-YAP1 tumor development." (PMID 39273023, 2024). "However, a pooled analysis of two trials evaluating the combined biomarkers of KRAS, NRAS, BRAF, and PIK3CA showed a significantly reduced benefit from anti-EGFR therapy in patients with any mutant tumor compared with patients with all wt tumors (interaction tests P < 0.05 for PFS, OS, and ORR)." (PMID 37974093, 2023). "In addition, we found that the patients with tumours with mutations in PIK3CA, BRAF, CDH1, and NRAS exhibit better survival outcomes than those without mutations in these genes." (PMID 37550388, 2023). "Additionally, GNAQ, GNAS, JAK2, NRAS, IDH2, and CTNNB1 are cancer-related genes that may be related to tumor metastasis." (PMID 36780540, 2023).